COL1A1 (collagen type I alpha 1 chain)
Diseases named in the same sentence as COL1A1 in open-access papers (continued):
Sharing a sentence is not in itself a finding about the gene and the disease.
osteogenesis imperfecta (continued). "The mutation of COL1A1 and COL1A2 in MSCs could cause osteogenesis imperfecta, it likely that COL1A1 and COL1A2 play an important role in osteogenesis differentiation from MSCs." (PMID 32489333, 2020). "Osteogenesis imperfecta (OI) is a phenotypically and genetically heterogeneous group of bone disorders characterized by bone fragility and skeletal deformity, owing to the abnormality of type I collagen formed by two α1(I) chains (encoded by COL1A1 gene) and one α2(I) chain (encoded by COL1A2 gene)." (PMID 31680973, 2019). "Indeed, mutations in collagen type I (COL1A1 and COL1A2) are responsible for mild to severe osteogenesis imperfecta that can be revealed in adulthood." (PMID 30283887, 2018). "The identification of human genes associated with bone fragility started around the 1990s through the study of monogenic syndromes with marked skeletal phenotypes such as osteogenesis imperfecta due to COL1A1 and COL1A2 defects and osteopetrosis due to TCIRG1 defects." (PMID 27533615, 2016). "Furthermore, three COL1A1 heterozygous variants were identified in three patients: two with an early onset glaucoma form and one with congenital glaucoma, two of them presenting also an early-onset cataract and mild form of osteogenesis imperfecta (OI)." (PMID 27484908, 2016). "In addition, 20 patients were diagnosed with Osteogenesis Imperfecta (OI) (OMIM: #166210, #259420, #166220), with ten patients showing variants in the COL1A2 gene (OMIM: *120160) and eight patients with variants in the COL1A1 gene (OMIM: *120150)." (PMID 40130161, 2025). "Notably, mutations in the COL1A1 and COL1A2 genes, responsible for encoding type I collagen, have been linked to the weakening of connective tissues and the onset of conditions such as osteogenesis imperfecta and Ehlers-Danlos syndrome." (PMID 38384607, 2024). "Mutations in the COL1A1 and COL1A2 genes, which encode type I collagen, are present in around 85%-90% of osteogenesis imperfecta (OI) patients." (PMID 37457877, 2023). "Currently only two mouse models have been reported for haploinsufficient (HI) mild Osteogenesis Imperfecta (OI); the Col1a1+/Mov13 (Mov13) and the Col1a1+/-365 mouse model." (PMID 36967771, 2023). "According to clinical presentation, radiographic findings, and family history, COL1A1/2 osteogenesis imperfecta (COL1A1/2-OI) is mainly classified into four types (I-IV) and is usually inherited in autosomal dominant (AD) pattern." (PMID 35804365, 2022). "The COL1A1 gene exhibits strong pleiotropy and contributes to the pathogenesis of a greater part of osteogenesis imperfecta (OI) and aEDS cases, and also a few cases of cEDS or vEDS." (PMID 35119775, 2022). "Finally, somatic mosaicism for a COL1A1 heterozygous pathogenic variant absent in the peripheral blood was identified in an adult with osteogenesis imperfecta/Ehlers-Danlos syndrome overlap." (PMID 34946877, 2021). "Osteogenesis imperfecta (OI) is a genetic disorder characterized by defects in COL1A1 and COL1A2, affecting bone, skin, and other tissue with high collagen content." (PMID 34532344, 2021). "Mutations in the type I collagen coding genes (COL1A1 and COL1A2) that affect collagen quantity or structure count to approximately 85% of osteogenesis imperfecta (OI) case." (PMID 34567078, 2021). "Therefore, this form of bone fragility is at the border of idiopathic osteoporosis and osteogenesis imperfecta, the difference being that osteogenesis imperfecta with COL1A1 mutations also affects eyes and ears rather than just bone." (PMID 30283887, 2018). "COL1A1/2-Osteogenesis Imperfecta (COL1A1/2-OI) follows an autosomal dominant inheritance pattern." (PMID 38392197, 2024). "Osteogenesis imperfecta/Ehlers−Danlos (OI/EDS) overlap syndrome is a recently described disorder of connective tissue, characterized by mutation of COL1A1 (17q21.33) or COL1A2 (7q21.3) genes, that are involved in α-1 and α-2 chains of type 1 collagen synthesis." (PMID 35456387, 2022).
osteogenesis imperfecta (continued). "Although the majority of heterozygous mutations in COL1A1 or COL1A2, encoding the pro-α1- and pro-α2-chain of type I collagen, respectively, result in the brittle bone disorder osteogenesis imperfecta (OI), specific type I collagen defects can also give rise to rare EDS subtypes." (PMID 34712265, 2021). "Osteogenesis imperfecta (OI), or “brittle bone disease,” is caused by mutations in the collagen type I genes COL1A1 and COL1A2 (or other collagen genes for rarer types of OI), causing production of a defective collagen type I that results in significant alterations in different tissues in the body." (PMID 30128210, 2018). "Congenital syphilis, skeletal dysplasia, and osteogenesis imperfecta (OI) were also considered in the differential diagnosis but were excluded after a negative skeletal dysplasia panel (including COL1A1) and negative quantitative rapid plasma reagin (RPR)." (PMID 41479472, 2025). "Similar findings have been reported for mutations in COL1A1 and COL1A2 that cause osteogenesis imperfecta, and whilst some mutations trigger the UPR, others do not." (PMID 41465495, 2025). "The infant sibling is healthy, with neither COL1A1 deletion nor features of osteogenesis imperfecta." (PMID 32281310, 2020). "Novel pathogenic variants were represented by 27 (42.85%) variants (20 in COL1A1; 7 in COL1A2) absent from the osteogenesis imperfecta variant database." (PMID 31447884, 2019). "For example, prenatal detection of a pathogenic COL1A1 variant in case 90-PRE facilitated coordinating an appropriate perinatal care plan and connecting the parents with other families with osteogenesis imperfecta (OI) so they could learn practical skills for caring for a baby with OI." (PMID 30266093, 2018). "Further investigations will be required to evaluate the mechanism by which such Col1a1 haploinsufficiency in CMV-Cre;Col1a1loxP/+ mice may lead to the phenotype similar to human type I Osteogenesis Imperfecta (OI)." (PMID 34893625, 2021). "Haploinsufficiency or gain of function mutations in COL1A1 and COL1A2, coding for the pro-collagen I chains, can cause different forms of osteogenesis imperfecta (OI) with (OMIM #259420) or without dentinogenesis imperfecta (DGI)." (PMID 32101163, 2020). "Osteogenesis imperfecta (OI) is known as brittle bone disease and is a rare, chronic, and currently noncurable disease characterized by inadequate formation of bone tissue due to a lack of collagen (mainly Col1A1 and Col1A2) or poor quality." (PMID 38459573, 2024).
pulmonary fibrosis (116 papers, 2008 to 2026). Chronic progressive interstitial lung disorder characterized by the replacement of the lung tissue by connective tissue, leading to progressive dyspnea, respiratory failure, or right heart failure. "Consistent with these pathological changes, the expression of collagen type 1 alpha 1 chain (COL1A1) and fibronectin, key markers associated with fibroblast activation during pulmonary fibrosis, was significantly elevated in the LPS group." (PMID 40898357, 2025). "Subsequently, the expression of COL1A1 protein in lung tissues was detected by western blot, associated with H&E and Masson staining for pulmonary fibrosis observation." (PMID 38709307, 2024). "Cluster 2 cells showed increased expression of POSTN and COL1A1 and other extracellular matrix genes implicated in pulmonary fibrosis." (PMID 33257409, 2020). "Together, these data show that loss of Fas signaling in Col1a1-expressing profibrotic fibroblasts also led to impaired homeostatic fibrosis resolution and persistent pulmonary fibrosis." (PMID 33290280, 2020). "In addition to the upregulation of typical fibrosis-associated genes (Col1a1, Fn1 and Acta2), an increase in Prrx1a and Prrx1b mRNA expression was previously reported during fibrosis development in the bleomycin model of lung fibrosis." (PMID 40856011, 2025). "Among those genes, we found that CAV1 and PECAM1 were specifically expressed in lung tissues, BMP4 and VEGFA were related to angiogenesis, FYN and SPP1 were related to immunity or inflammation, and COL1A1 was closely associated with pulmonary fibrosis according to the GeneCards database." (PMID 37794454, 2023). "By searching the 18 candidate hub genes in GeneCards database, we found that CAV1 and PECAM1 were specifically expressed in lung tissues, BMP4 and VEGFA were related to angiogenesis, FYN and SPP1 were related to immunity or inflammation, and COL1A1 was closely associated with pulmonary fibrosis." (PMID 37794454, 2023). "Type I collagen, which is the major component of pulmonary fibrosis, is encoded by the COL1A1 gene." (PMID 30347679, 2018). "In vitro, we evaluated the activity of PIPE-791 using primary human lung fibroblasts whereby LPA addition induces COL1A1 production and promotes chemotaxis, two functions linked to LPAR1 activation and contribute to lung fibrosis." (PMID 40887574, 2025). "We also found the decreased expression of the pulmonary fibrosis‐related gene Col1a1 and reduced protein levels of COL1A1 and TGF‐β in CA‐treated lung tissues." (PMID 41476649, 2025). "Knockdown of CCL2 expression alleviated pulmonary fibrosis and reduced the expression of COL1A1 protein and α-SMA protein." (PMID 40606673, 2025). "COL6 was found to have increased mRNA and protein deposition in the lung of patients with pulmonary fibrosis, and COL1A1 was highly expressed in RILI." (PMID 41394148, 2025). "At 21 d.p.i., deletion of both Yap and Taz in myofibroblasts strongly attenuated lung fibrosis and suppressed the expression of key myofibroblast activation and profibrotic genes, including Acta2, Col1a1, Postn, Fn1, Col3a1, and Tgfb1." (PMID 40454481, 2025). "Western blot analysis of MRC5 further confirmed that the longer the duration of TGFβ treatment, the higher the expression of lung fibrosis markers (including COL1A1 and Vim), but the lower the expression of RTN3." (PMID 39972424, 2025). "ECM proteins, like α-SMA, FN, and COL1A1, are important fibrotic markers during the fibrotic progression of pulmonary fibrosis." (PMID 41007776, 2025). "Though the mice were exposed to the same amount of CS particles in total, repeated exposure resulted in severe pulmonary fibrosis, which was demonstrated by Masson’s trichrome staining and elevated Col1a1 and Fn transcripts." (PMID 39122899, 2024). "Overall data suggest COL1A1 as the main and common early marker gene for the incidence of cardiac and pulmonary fibrosis." (PMID 39388499, 2024).
pulmonary fibrosis (continued). "Immunohistochemical analysis revealed significant reductions in the protein expression of α-SMA and COL1A1, which are typical protein markers of lung fibrosis, following the inhalation of AS@PPGC NPs, LIG@PPGC NPs, and AS_LIG@PPGC NPs." (PMID 38166847, 2024). "Through competition with miR-196a, H19 participates in the regulation of COL1A1, thereby mediating pulmonary fibrosis." (PMID 39944354, 2024). "Lead compounds J27644 (4, HDAC6/8 inhibitor, IC50s 13 and 151 nM, respectively) and 5 (HDAC6 inhibitor, IC50 = 62 nM) reduced α-SMA and Col1a1 protein levels and efficiently modulated fibroblast survival, countering pulmonary fibrosis." (PMID 39766311, 2024). "It was found that LPS triggered pulmonary fibrosis obviously according to H&E and Masson staining images and rising level of collagen 1 α1 (COL1A1) protein." (PMID 38709307, 2024). "In fact, the targeting of COL1A1 by miR-133a is an important factor in its involvement in pulmonary fibrosis." (PMID 37936707, 2023). "The levels of lung fibrosis markers, including Timp1, collagen type I alpha 1 chain (Col1a1), and alpha-smooth muscle actin (α-SMA) mRNAs, were highest in bleomycin-treated alcohol-fed mice." (PMID 37457733, 2023). "Increased COL1A1 mRNA expression in bronchoalveolar lavage cells from human patients suffering from idiopathic pulmonary fibrosis and lung cancer is presumed to be the consequence of DNMT1 regulation, although the underlying mechanism remains to be elucidated." (PMID 37373151, 2023). "In fact, a miR-29a mimic has been developed to target COL1A1 as a treatment option for pulmonary fibrosis." (PMID 37936707, 2023). "JTE-013 also inhibited the expression of fibrosis markers α-SMA, MMP-9, and COL1A1, and alleviated the symptoms of pulmonary fibrosis." (PMID 37895915, 2023). "Studies have shown that lncRNA H19 promotes bleomycin-(BLM) induced pulmonary fibrosis by regulating the miR-196a/COL1A1 pathway." (PMID 36478088, 2023). "Similar to the results in lung fibrosis, expression of Col1a1, Col1a2, and Acta2 was inhibited in MHP1-AcN-treated mice." (PMID 35864207, 2022). "Whereas patients with lower viral loads and more severe lung lesions had more macrophages, CD8+T lymphocytes, and enriched pathways for COL1A1 and other markers of pulmonary fibrosis." (PMID 36027872, 2022). "In contrast, patient lung tissue samples containing low levels of SARS-CoV-2 RNA show enrichment for COL1A1 and other markers of pulmonary fibrosis." (PMID 35233546, 2022). "In pulmonary fibrosis, H19 binds miR-29b, miR-423-5p, and miR-196a to silence the translation of Col1a1 (collagen, type I, alpha 1), Foxa1 (forkhead box A1), and COL1A1 mRNAs, respectively." (PMID 35893236, 2022). "Unsurprisingly, qRT-PCR of Col1a1, and Fn1 also indicated that the TL treated mice exhibited a lower degree of lung fibrosis than the BIM treated mice." (PMID 33995084, 2021). "Our work also infers to a less characterised role of airway macrophages in pulmonary fibrosis, as it demonstrates a link between the macrophage derived expression of COL1A1 and fibrotic disease pathogenesis." (PMID 34867934, 2021). "During lung fibrosis, the expression of Acta2 and collagen 1a1 (Col1a1) and 3a1 (Col3a1) in the PDGFR-β+ cell lineage is markedly increased." (PMID 34893592, 2021). "We further found that lung fibrosis and the expression of fibrosis genes, including Col1a1, Col3a1 and Fn1, an outcome mediated by the accumulation of senescence, were reduced by SSK1 treatment." (PMID 32341413, 2020). "In summary, our present data supports SOX2 regulation of COL1A1 promoter as a potential target in BP treatment of pulmonary fibrosis." (PMID 30287739, 2018). "Extracellular matrix protein and gene expression of markers involved in lung fibrosis (tenascin-c, fibronectin, collagen I [COL1A1], collagen III [COL3A1] and α-smooth muscle actin [α-SMA]) were analyzed." (PMID 29703175, 2018).
pulmonary fibrosis (continued). "The lung fibrosis was examined by Masson’s trichrome (MT) stain of paraffin sections and mRNA expression levels of Col1a1, Col3a1, and Acta2 in different frozen lung samples." (PMID 29497425, 2018). "However, pulmonary fibrosis, as assessed by MT staining, was comparable between genotypes, although Col1a1 expression was lower in lungs from HFD‐fed Angptl2−/− mice." (PMID 41508557, 2026). "Importantly, mice with Nudt21 deletion in Col1a1 expressing cells aggravated bleomycin-induced pulmonary fibrosis." (PMID 40738116, 2025). "α-SMA and COL1A1 are usually used as biomarkers to evaluate the degree of pulmonary fibrosis." (PMID 39575431, 2024). "Furthermore, we assumed that the overexpression of these genes in PBMCs would be relevant to pulmonary fibrosis in the same way as in pulmonary fibroblasts (e.g., COL1A1 and SERPINE1)." (PMID 38612561, 2024). "They showed that systemic, intravenous injection of human umbilical cord MSC-Exos completely suppressed the development and progression of pulmonary fibrosis in experimental animals by down-regulating gene expression of collagen type I alpha 1 (COL1A1) and fibronectin (FN)." (PMID 38673961, 2024). "Also, FPNI treatment prevented the upregulation of senescence markers that are well-known to be associated to lung fibrosis, such as TNF-α, Il6, Cdkn1a and Cdkn1b along with that of collagen isoforms Col1a1 and Col3a1." (PMID 38167804, 2024). "In our study, α-SMA and COL1A1 were measured to assess the degree of pulmonary fibrosis." (PMID 39575431, 2024). "Notably, the expressions of periostin, fibronectin, and Col1a1 were significantly reduced in rs35705950 TG mice with lung fibrosis relative to their WT counterparts." (PMID 39329706, 2024). "Notably, we found that intranasal administration of PNA-33 markedly reduces lung fibrosis, as indicated by a significant decrease in collagen content and fibrogenic gene expression (Col1a1 and Acta2) compared with mice treated with scrambled control." (PMID 36626225, 2023). "Therefore, pulmonary fibrosis in both humans and mice is associated with increased TKS5 expression, consistently correlated with the expression of Col1a1, especially in LFs." (PMID 37735172, 2023). "However, the inactivation of Yap1 by itself in AT2 cells resulted in increased AT2 to AT1 cell differentiation and decreased pulmonary fibrosis based on hydroxyproline content and significantly less Col1a1 and Col3a1 RNA expression." (PMID 37166104, 2023). "Therefore, COL1A1 plays an important role in pulmonary fibrosis, and interstitial lung disease (ILD) is an important complication of SSc." (PMID 36873898, 2023). "Comparison of interactome of Col4a1 and Col4a2 with interactome of Col1a1, a key molecular determinant of pulmonary fibrosis, revealed their significant similarity—approximately 77% of partner genes of Col4a1 and Col4a2 retrieved from STRING database were found to be first neighbors of Col1a1." (PMID 35625754, 2022). "A previous study showed that miR-196a directly regulated Col1a1 and Col3a1 expression in keloid fibroblasts 46, and miR-196a/Col1a1 has been reported to participate in pulmonary fibrosis 47, though its roles in CFs and cardiac fibrosis remain unknown." (PMID 34158869, 2021). "This confirmed once again that lncRNA H19 could promote the expression of COL1A1 through the competitive binding of microRNA-196a and accelerate the process of pulmonary fibrosis." (PMID 33817326, 2021). "The miR-196a/COL1A1 axis is known to be regulated by lncRNA H19 in pulmonary fibrosis." (PMID 33511215, 2021). "Among them, 27/RdRP was functionally validated to target the nsp12 region of SARS-CoV-2, confirmed for its transcriptome-wide activity, similar to antifibrotic miR-27a, and experimentally proven to suppress TGF-β-induced lung fibrosis and a collagen-producing gene, COL1A1, in human lung cells." (PMID 34580386, 2021).